RRM2 (ribonucleotide reductase regulatory subunit M2)
Diseases named in the same sentence as RRM2 in open-access papers (continued):
Sharing a sentence is not in itself a finding about the gene and the disease.
viral infection (2 papers, 2023 to 2024). "Ribonucleotide reductase M2 (RRM2) is also involved in the maintenance of viral infection, playing a key role in the synthesis of 2′-deoxyribonucleoside 5′-diphosphates essential for DNA biosynthesis, replication and repair." (PMID 39596028, 2024). "The data presented herein provide novel experimental evidence about the role of the RRM2 α3 helix in La—HCV-IRES interaction and insights into the modulatory role of the La protein during translation regulation upon viral infection." (PMID 36768895, 2023).
adrenocortical adenoma (1 paper, 2021). "Moreover, comparative reanalysis of publicly available microarray datasets indicated upregulation of RRM2 in ACC compared to adrenocortical adenoma (ACA) and that, in selected ACC samples, RRM2 correlated well with the specific Ki67 indices of these tumors." (PMID 34439352, 2021).
anaplastic carcinoma (1 paper, 2025). "In thyroid, RRM2 nuclear overexpression was seen in PTC and anaplastic carcinoma." (PMID 40420140, 2025).
aplastic anemia (1 paper, 2022). Anemia resulting from bone marrow failure (aplastic or hypoplastic bone marrow). "Abnormal gene expression exists in children with idiopathic severe aplastic anemia, and RRM2, TTK, and TYMS in children's MSCs are significantly down-regulated." (PMID 35082972, 2022).
benign prostatic hyperplasia (1 paper, 2023). A non-cancerous nodular enlargement of the prostate gland. "RRM2 expression was analyzed in normal prostate epithelium tissues from thirty patient diagnosed with benign prostatic hyperplasia (BPH) and sixty pairs of prostate tumor tissues with adjacent normal prostate tissues from sixty patients diagnosed with PCa by quantitative real-time PCR analysis." (PMID 37596700, 2023).
cardiomyopathy (1 paper, 2022). A disease of the heart muscle or myocardium proper. "Our study revealed the potential protective function of RRM2 on DOX-induced cardiomyopathy and investigated the underlying mechanism." (PMID 35204799, 2022). "As predicted, RRM2 overexpression ameliorated DOX-induced cardiomyopathy, indicated by reduced pro-apoptotic and autophagy-related proteins and improved myofibrillar degeneration and disruption." (PMID 35204799, 2022). "Consistently, RRM2 knockdown aggravated the development of DOX-induced cardiomyopathy, which could be connected to the disturbance of apoptosis and autophagy." (PMID 35204799, 2022). "In summary, we believe that RRM2 could be a promising therapy against DOX-induced cardiomyopathy." (PMID 35204799, 2022). "However, the connection between RRM2 and the AKT/mTOR signaling pathway in DOX-induced cardiomyopathy remains unclear." (PMID 35204799, 2022).
cervical (1 paper, 2014). "RRM2 overexpression has been correlated with cervical carcinogenesis." (PMID 24637958, 2014).
CHARGE syndrome (1 paper, 2023). CHARGE syndrome is a multiple congenital anomaly syndrome characterized by the variable combination of multiple anomalies, mainly Coloboma; Choanal atresia/stenosis; Cranial nerve dysfunction; Characteristic ear anomalies (known as the major 4 C's). "In human disease with “ribosomopathy”, some germline variants of the FIR/PUF60 gene, generating truncated protein lacking RRM1, RRM2, P62-binding site, or RRM3/UHM, have been reported in Verheij and CHARGE syndromes." (PMID 38139171, 2023).
Cholecystitis (1 paper, 2021). The presence of inflammatory changes in the gallbladder. "As a novel identified RRM2 inhibitor, osalmid has been approved for treating cholecystitis, inflammation, and postcholecystectomy syndrome, which inhibited RRM2 activity by binding to hydrogen bond of RRM2." (PMID 34567073, 2021).
chronic myelogenous leukaemia (1 paper, 2022). "HU is a typical RNR inhibitor that targets RRM2 and has long been used for cancer therapy in the clinic, including chronic myelogenous leukaemia, AML, and other haematological malignancies." (PMID 36230632, 2022).
Cirrhosis (1 paper, 2024). A chronic disorder of the liver in which liver tissue becomes scarred and is partially replaced by regenerative nodules and fibrotic tissue resulting in loss of liver function. "In HBV-related cirrhosis, HBV-related HCC, and its corresponding noncancerous tissues, obvious HBx expression was displayed, and strong positive RRM2 staining was much deeper in HCC tissues than in cirrhosis tissues." (PMID 39256879, 2024). "The aim was to investigate the expression pattern of RRM2 during the progression from cirrhosis to HCC and explore the relationship between its expression level in HCC and the pathological stage of the disease." (PMID 39256879, 2024). "It is worth mentioning that RRM2 exhibited a discernible pattern of heightened expression levels during the progression from cirrhosis to HCC disease stage." (PMID 39256879, 2024). "HBx and RRM2 protein expression was observed by Immunohistochemistry (IHC) staining in 10 HBV-related cirrhosis tissues, with 151 pairs of HCC tumor tissues and adjacent paraneoplastic tissues (85 of which were HBV-related HCC)." (PMID 39256879, 2024). "In addition, the expression of RRM2 also depicted an upward trend between cirrhosis and HCC in GSE10143, GSE54236, GSE25097 and GSE17548 datasets from GEO database." (PMID 39256879, 2024).
dengue (1 paper, 2023). "The GO analysis revealed that the genes BUB1, RRM2, IFI27, DLGAP5, and CEP55 exhibit 4-fold up-regulation in dengue and SD patients however, they exhibit downregulation in CP." (PMID 38076406, 2023).
developmental delay (1 paper, 2022). "Recently, a mild form of TARP with developmental delay and dysmorphic traits was reported in the patient having a missense mutation (NM_005676: c.965C>T, p.P322L) in the RRM2 RNA binding domain in RBM10." (PMID 36421828, 2022).
diffuse large B-cell lymphoma (1 paper, 2024). "Notably, the genomic alteration types in all diffuse large B-cell lymphoma (DLBCL) and KICH cases were deep deletions in RRM2." (PMID 38635758, 2024).
fatty liver (1 paper, 2016). "From the present results, we identified Iah1 and Rrm2 as candidate genes in the liver for the development of fatty liver." (PMID 27855657, 2016).
gallbladder cancer (1 paper, 2025). "Quantification of IHC H-scores indicated that both E2F8 and RRM2 were significantly upregulated in recurrent compared with primary gallbladder cancers." (PMID 41392282, 2025).
hepatitis C (1 paper, 2024). "RRM2 was also upregulated in response to hepatitis C virus infection and may regulate hepatitis C RNA synthesis." (PMID 39596028, 2024).
hepatoblastoma (1 paper, 2023). Hepatoblastoma (HB) is a malignant hepatic tumor and is the most common pediatric liver cancer. "In hepatoblastoma, the RRM2 subunit of ribonucleotide reductase is associated with disease progression, but in response to chemotherapy, subunit switching favours the less active RRM2B subunit which supports hepatoblastoma cell survival and relapse." (PMID 36882565, 2023).
liposarcoma (1 paper, 2021). A usually painless malignant tumor that arises from adipose tissue. "Our previous studies have indicated that TYMS and RRM2 are key genes in liposarcoma development and progression." (PMID 34868934, 2021). "Western blotting verified that Apatinib downregulated the TYMS/STAT3/PD-L1 pathway and inhibited liposarcoma proliferation by suppressing the RRM2/PI3K/AKT/mTOR pathway." (PMID 34868934, 2021). "While the previous study revealed TYMS downregulation inhibited STAT3 phosphorylation in liposarcoma cell and RRM2 downregulation inhibited the AKT signaling pathway." (PMID 34868934, 2021). "Apatinib might inhibit liposarcoma cell proliferation through the RRM2/PI3K/AKT/mTOR signaling pathway and downregulate PD-L1 via the TYMS/STAT3 signaling pathway." (PMID 34868934, 2021). "To determine whether Apatinib modulates liposarcoma cell proliferation through the RRM2/PI3K/AKT pathway, we used WB to measure the protein levels of RRM2, PI3K, p-PI3K, AKT, p-AKT, mTOR, and p-mTOR." (PMID 34868934, 2021). "Apatinib may inhibit liposarcoma cell proliferation through RRM2/PI3K/AKT/mTOR signaling pathway, and down-regulate PD-L1 through TYMS/STAT3 signaling pathway." (PMID 34868934, 2021). "Besides, our studies also found that TYMS and RRM2 mRNA expression was higher in liposarcoma than normal adipose tissues and that TYMS overexpression was associated with poor prognosis in liposarcoma patients." (PMID 34868934, 2021).
liver diseases (1 paper, 2023). "There is a need for further investigations to clarify the mechanisms and functions of RRM2 in HCV-related liver diseases, particularly in HCC." (PMID 36768940, 2023). "RRM2 functions as a pro-viral factor essential for HCV RNA synthesis, but its functional role in HCV-induced liver diseases remains unknown." (PMID 36768940, 2023).
liver fibrosis (1 paper, 2023). "The result showed that the BUB1B and RRM2 genes were hub genes in AFB1-liver fibrosis-HCC progression." (PMID 36829489, 2023). "the top ten core genes were identified using four different algorithm methods and the combined the combined core genes showed that the BUB1B and RRM2 genes were core genes of AFB1-liver fibrosis-HCC." (PMID 36829489, 2023). "Concluded, the core genes of AFB1-liver fibrosis-HCC were BUB1B and RRM2 genes." (PMID 36829489, 2023).
lung neoplasm (1 paper, 2024). A benign or malignant, primary or metastatic neoplasm involving the lungs. "Earlier studies demonstrated that broad overexpression of Rrm2 or Rrm2b induces lung neoplasms in transgenic mice." (PMID 39360631, 2024).
metabolic syndrome (1 paper, 2016). A cluster of metabolic risk factors for CARDIOVASCULAR DISEASES and TYPE 2 DIABETES MELLITUS. "However, there are no SNPs associated with metabolic syndrome in 4 candidate genes (Iah1, Rrm2, Zfp125, and Nrcam)." (PMID 27855657, 2016).
metastatic tumors (1 paper, 2023). "IHC on PNR tumors using an antibody recognizing both Rrm2 and Rrm2B proteins showed an increase of the number of (Rrm2 + Rrm2B)+ cells in the metastatic tumors compared to the primary tumors." (PMID 36882565, 2023).
mitochondrial DNA depletion syndrome (1 paper, 2023). The mitochondrial DNA (mtDNA) depletion syndrome (MDS) is a clinically heterogeneous group of mitochondrial disorders characterized by a reduction of the mtDNA copy number in affected tissues without mutations or rearrangements in the mtDNA. "RRM2 is associated with a rare disease known as mitochondrial DNA depletion syndrome and is linked to mitochondrial DNA copy number in various models." (PMID 37239369, 2023). "Mitochondrial DNA depletion syndrome is marked by malfunctions in mitochondrial DNA synthesis, reduced mitochondrial quantity, diverse clinical symptoms, and high infant mortality rates, possibly due to depletion of the nucleotide pools that RRM2 generates." (PMID 37239369, 2023).
Multiple Organ Failure (1 paper, 2017). A progressive condition usually characterized by combined failure of several organs such as the lungs, liver, kidney, along with some clotting mechanisms, usually postinjury or postoperative. "Although Rrm2 knockout mice also displayed multiple organ failure, the status of the pancreas was not indicated in this report." (PMID 28135283, 2017).
myeloid leukemia (1 paper, 2015). A clonal proliferation of myeloid cells and their precursors in the bone marrow, peripheral blood, and spleen. "Moreover, treatment of myeloid leukemia cells with 5-aza-2′-dC and the RRM2-inhibitor HU together synergistically inhibited cell proliferation and altered DNA methylation levels in these cancer cell lines in a dose-dependent manner." (PMID 26468331, 2015).
neurofibroma (1 paper, 2017). An intraneural or extraneural neoplasm arising from nerve tissues and neural sheaths. "PLK1,RRM1, and RRM2 mRNA levels were increased in MPNST compared to benign neurofibroma tissue, and the protein level of PLK1 was increased in the MPNST cell lines compared to normal Schwann cells, indicating an increased dependence on these drug targets in malignant cells." (PMID 28556483, 2017). "We did not observe any significant difference in RRM1 or its activator and binding partner RRM2 in the MPNST cell lines as compared to HSC1; however, these genes were both significantly upregulated in MPNST patient tumor samples as compared to benign neurofibromas." (PMID 28556483, 2017).
osteoporosis (1 paper, 2025). A condition of reduced bone mass, with decreased cortical thickness and a decrease in the number and size of the trabeculae of cancellous bone (but normal chemical composition), resulting in increased fracture incidence. "RRM2 may regulate the osteogenic differentiation of MEFs via the classical Wnt/β-catenin signaling pathway, providing a potential target for the treatment of osteoporosis." (PMID 40299567, 2025).
papillary thyroid carcinoma (1 paper, 2025). "When cases were grouped by pathological subtype, RRM2 expression was higher in classic and tall-cell variants of papillary thyroid carcinoma compared with the follicular variant." (PMID 41333212, 2025). "We performed a detailed analysis of RRM2 expression based on TNM stages and pathological types using the TCGA data, When cases were grouped by pathological subtype, RRM2 expression was higher in classic and tall-cell variants of papillary thyroid carcinoma compared with the follicular variant." (PMID 41333212, 2025). "The results showed that the expression of RRM2 was significantly higher in papillary thyroid carcinoma tissues than in paracancerous thyroid epithelial tissues (P<0.01), and this trend was verified in most samples." (PMID 41333212, 2025).
post-traumatic stress disorder (1 paper, 2024). An anxiety disorder precipitated by an experience of intense fear or horror while exposed to a traumatic (especially life-threatening) event. "DNA methylation in or near RRM2 has also been associated with schizophrenia and post-traumatic stress disorder (PTSD), two psychosocial disorders related to psychosocial stress." (PMID 38431869, 2024).
progeria (1 paper, 2020). "In contrast to their effect in the context of progeria, the lifespan of Chk1, Rrm2 and Chk1/Rrm2 transgenic mice was similar to WT littermates in physiological settings." (PMID 32253367, 2020).
prostate tumor (1 paper, 2023). "In addition, we analyzed RRM2 expression in subgroups of PCa patients and found that RRM2 was significantly overexpressed in prostate tumor samples with a high Gleason score (Gleason score > 7)." (PMID 37596700, 2023). "Data from TCGA databases suggested that SNHG4 expression was significantly correlated with the expression of RRM2, EZH2, AURKA and TK1 in prostate tumor samples (p < 0.01)." (PMID 37596700, 2023).
proteinopathies (1 paper, 2023). "Taken together, high-affinity antibodies targeting the RRM2 or the C-terminal low complexity domain potently suppress TDP-43 phase separation, aggregation, and cellular aggregate uptake, all processes implicated in TDP-43 proteinopathies." (PMID 37434215, 2023).
psoriasis (1 paper, 2025). An autoimmune condition characterized by red, well-delineated plaques with silvery scales that are usually on the extensor surfaces and scalp. "Notably, RRM2 was identified as the most significant differentially expressed gene between the psoriasis and control groups and is critical in cell proliferation." (PMID 40735322, 2025).
rhabdomyosarcoma (1 paper, 2017). A rare aggressive malignant mesenchymal neoplasm arising from skeletal muscle.
serous ovarian cancer (1 paper, 2021). "This showed that higher expressions of CDCA3, CENPF, NCAPG, RRM2, UBE2C, and NBEA were associated with worse OS regardless of serous ovarian cancer stages." (PMID 34577856, 2021).
Stroke (1 paper, 2019). Sudden impairment of blood flow to a part of the brain due to occlusion or rupture of an artery to the brain. "However, literature retrieval results showed little evidences that other hub genes MPP4, RRM2, RRM2B, RRM1 and VCP contributed to the molecular mechanism of stroke prognosis." (PMID 31690277, 2019).
thyroid (1 paper, 2025). "This study focuses on analysing the expression of CD56, HBME-1, RRM2 and APLP2 IHC markers in NIFTP versus other thyroid follicular lesions and their diagnostic validity was also evaluated." (PMID 40420140, 2025). "Moreover, Amyloid precursor-like protein 2 (APLP2), Ribonucleotide reductase M2 polypeptide (RRM2) and Protein Regulator of cytokinesis 1 (PRC1) are new indicators studied to differentiate thyroid follicular lesions." (PMID 40420140, 2025).
thyroid tumor (1 paper, 2025). A benign or malignant neoplasm affecting the thyroid gland. "support the hypothesis that RRM2 is associated with more aggressive thyroid tumors and may therefore have potential utility as a biomarker to distinguish higher-risk or more invasive disease phenotypes." (PMID 41333212, 2025). "RRM2 is a tumor-promoting gene that correlates with aggressive clinicopathologic features and functionally drives thyroid tumor growth in vitro and in vivo." (PMID 41333212, 2025).
tongue cancer (1 paper, 2022). A malignant neoplasm affecting the tongue. "Among them, AC099850.3 is the most co-expressed lncRNA, which is related to six differently expressed mRNAs, namely (CAV1, NRAS, ACSL3, AURKA, EIF2AK4 and RRM2), and its high expression level is closely related to the reduction in the survival rate of patients with tongue cancer." (PMID 35299954, 2022).
trisomy (1 paper, 2023). A chromosomal abnormality consisting of the presence of one chromosome in addition to the normal diploid number. "Τhe association between high RRM2 mRNA levels and trisomy 12 found in our study raises questions regarding the existence of a relationship and its potential clinical utilization." (PMID 36811764, 2023).
uterine carcinosarcoma (1 paper, 2024). A usually aggressive malignant neoplasm arising from the uterine corpus and less often the cervix. "The analysis data revealed that RRM2 exhibited the highest alteration frequency (>7%) in patients with uterine carcinosarcoma, among which "amplification" was the main type." (PMID 38635758, 2024). "We observed a positive correlation between RRM2 expression and MSI for COAD, LIHC, SARC, STAD, TGCT, UCEC, and UCS (Uterine Carcinosarcoma) but a negative correlation for LAML and SKCM." (PMID 38635758, 2024).
Verheij syndrome (1 paper, 2023). "The germline mutation of FIR in RRM1 + RRM2 of CHARGE or Verheij syndrome would provide insights into the role of FIR variants in inhibiting homodimerization and affecting rRNA and mRNA transcription." (PMID 38139171, 2023).